SST (somatostatin)
Diseases named in the same sentence as SST in open-access papers (continued):
Sharing a sentence is not in itself a finding about the gene and the disease.
epilepsy (35 papers, 2011 to 2026). A brain disorder characterized by episodes of abnormally increased neuronal discharge resulting in transient episodes of sensory or motor neurological dysfunction, or psychic dysfunction. "Collectively, our results establish MINAR1 as a key regulator of seizure susceptibility, likely via Gαs-cAMP-dependent modulation of SST+ interneurons, offering a molecular framework for developing targeted epilepsy therapies." (PMID 41640244, 2026). "The most notable gene expression changes associated with epilepsy were found in a few groups of principal neurons (L5-6_Fezf2 and L2-3_Cux2) and GABAergic interneurons (somatostatin (SST)+ and parvalbumin (PV)+ types)." (PMID 39937026, 2025). "In particular, a loss of somatostatin-positive interneurons in the amygdala has been demonstrated in experimental epilepsy models." (PMID 39746805, 2025). "Loss of inhibitory interneurons is common in epilepsy, with SST interneurons being especially vulnerable." (PMID 39497922, 2024). "Recent studies have revealed that alterations or immaturity in GABAergic functioning, particularly involving SST+ interneurons, are associated with seizure disorders." (PMID 38714540, 2024). "Genes associated with epilepsy were specifically enriched in excitatory neurons located in cortical layers 4–6 (C36) and SST-expressing inhibitory neurons (C6)." (PMID 39363111, 2024). "This rapid PV+ cell loss was in contrast with the neurodegeneration of SST+ neurons, which occurred in the dentate gyrus later during the chronic stage of the epilepsy." (PMID 38563502, 2024). "For what concerns the SST-positive neurons, studies on human and mouse models, both in vivo and in vitro, have provided evidence for a correlation between epilepsy and the loss of this CIN population." (PMID 36568982, 2022). "GIN cells belong to the class of somatostatin-expressing inhibitory interneurons that have been implicated in several aspects of epilepsy." (PMID 22783167, 2012). "Dysfunction of somatostatin cells has therefore been postulated to underlie some forms of experimental or poststatus epilepticus seizure disorders." (PMID 21876820, 2011). "The intricate connection between SST+ interneurons and seizures goes beyond a simple association, exemplified by a decrease in SST+ interneuron activity in the neocortex observed in Dravet syndrome, an example of a monogenic epilepsy caused by a pathogenic variant in the SCN1A gene." (PMID 38714540, 2024). "We also observed an enrichment of developmental delay and epilepsy genes among downregulated genes in SST+ neocortical interneurons." (PMID 37782669, 2023). "The role of somatostatin in epilepsy was suggested by Vezzani and Hoyer (1999) because somatostatin is released during seizures." (PMID 35204812, 2022). "Previously, involvement of neurons in epilepsy has been mainly studied layerwise for principal neurons or for cardinal types of GABAergic interneurons, e.g., PV, SST, or VIP5,41,42." (PMID 33028830, 2020). "Electrophysiological studies on in vitro models of epilepsy have provided evidence that somatostatin acts in CA1 and CA3 to reduce hyper-excitability." (PMID 31117258, 2019). "The role of somatostatin in the etiopathogenesis of epilepsy is a further example of how this peptide is required to maintain network stability." (PMID 31117258, 2019). "Mainly, they display slightly impaired insulin and somatostatin secretion, mild cardiac arrhythmia, and they are less prone to epilepsy." (PMID 31827421, 2019). "Significant findings included reduction in somatostatin neurons and neurokinin 1 receptor labelling in the ventrolateral medulla in sudden death in epilepsy compared to controls (P < 0.05)." (PMID 29608654, 2018). "SST SOMA+-labelled neurons represented from 22% (in non-epilepsy controls) to 26% (in Dravet syndrome) of all VLM neurons between the groups; total neuronal counts varied between groups but without significance." (PMID 29608654, 2018).
epilepsy (continued). "Postinjury connectivity of CA3 pyramidal cells is not limited to the somatostatin-positive hilar inhibitory interneurons, and backprojections to DGCs have been proposed as a potential form of hippocampal reorganization in epilepsy." (PMID 29085896, 2017). "In this study, we examined SST interneuron activity in the in vitro 4-aminopyridine (4-AP) model of epilepsy." (PMID 24465989, 2014). "This gene is very relevant for epilepsy since it codes for a receptor of the endogenous antiepileptic somatostatin." (PMID 22022585, 2011). "Hippocampal somatostatin-positive interneurons appear to be particularly sensitive to seizure-induced damage as demonstrated in animal models of drug-induced epilepsy, as well as in patients with chronic temporal lobe epilepsy." (PMID 21876820, 2011). "For example, while our focus on PV+ interneurons was derived in part from the expression of the α2δ-2 protein in this cell type, other interneuron types, such as somatostatin-expressing interneurons, also decrease in density in certain forms of epilepsy and were not examined here." (PMID 38749701, 2024). "Similar changes among SST interneurons have been identified in other epilepsy models with disparate etiologies, suggesting that this population of interneurons may be particularly important for maintaining excitatory/inhibitory balance in the face of insult." (PMID 39497922, 2024). "Given the implication of SST+ interneurons in network dysfunction and epilepsy, it is plausible that their distinct characteristic may contribute to differential effects on GABAA receptor affinity." (PMID 38714540, 2024). "Meanwhile, the novel demonstration of deep layer inhibition during specific activation of SST interneurons could potentially be used to shut down aberrant neuronal activity, thus offering therapeutic strategies for diseases such as epilepsy." (PMID 31746324, 2020). "Furthermore, there was evidence for variation with duration of epilepsy for somatostatin and neurokinin 1 receptor." (PMID 29608654, 2018). "In the context of epilepsy, the targeting of PV interneurons may also be more preferable because there are reports that SST interneurons become depleted, whereas PV interneurons survive in epileptic animals and epilepsy patients." (PMID 30233328, 2018). "Similarly, various forms of epilepsy, such as temporal lobe epilepsy, SCN8A epileptic encephalopathy, and Dravet syndrome, are associated with an imbalanced E-I ratio arising from dysfunction in SST and PV interneurons." (PMID 37545878, 2023). "At this point, we cannot entirely rule out that a reduced expression of parvalbumin and somatostatin takes place in cellular subcompartments of interneurons within the GGs without loss of the cells themselves − similar to what has been suggested in epilepsy-associated hippocampal sclerosis." (PMID 36538906, 2022). "Our results indicate that very few specific subtypes of PV, SST, and VIP neurons make predominant contributions to the pathology of epilepsy." (PMID 40313715, 2025). "First, given that GluN2A subunits contribute significantly to PV and SSt IN synaptic NMDARs, this heterogeneity emphasizes the need to further elucidate the role of these neurons in epileptic syndromes, as the GluN2A subunit may be a critical determinant of some forms of epilepsy." (PMID 34326063, 2021). "Higher SST and NK1R labelling index was also noted in cases with epilepsy chronicity of >10 years, particularly the epilepsy control group (P ≤ 0.025)." (PMID 29608654, 2018). "There was also a trend for increased labelling with SST and NK1R in patients with epilepsy duration of a decade or more suggesting adaptive modulation of these systems can occur." (PMID 29608654, 2018). "For SST-PERIPH+, lower densities were noted for all epilepsy groups compared to non-epilepsy controls at all obex levels, with greatest significant at obex 7–8 mm (definite SUDEP: non-epilepsy sudden death controls) (P < 0.05)." (PMID 29608654, 2018).
acromegaly (28 papers, 2012 to 2026). Acromegaly is an acquired disorder related to excessive production of growth hormone (GH) and characterized by progressive somatic disfigurement (mainly involving the face and extremities) and systemic manifestations. "For example, acromegaly is caused by excessive production of growth hormone in the pituitary gland, and SST analogs such as octretotide and lanreotide are clinically used for treating acromegaly by exploiting the inhibitory role of SST via SSTR." (PMID 35446253, 2022). "Aggressive somatotroph pituitary tumor that causes acromegaly is extremely rare and resists conventional treatments such as multiple surgeries, radiotherapies, and various types of somatostatin analogs." (PMID 35712496, 2022). "A clinical study in patients with acromegaly, a condition characterized by chronic excess of GH, showed that patients with acromegaly also have high levels of somatostatin and concluded that excess GH could be a causal factor in somatostatin hypersecretion." (PMID 37855319, 2024). "This case highlights the potential role of combined somatostatin analogs and dopamine agonists in selected patients with acromegaly." (PMID 41664776, 2026). "In clinical practice, acromegaly is pharmacologically treated by dose titration of somatostatin agonists where the goal is to maximize the suppression of GH secretion at the pituitary somatotrophs, which results in suppression of serum IGF-1." (PMID 35000098, 2022). "The antiproliferative action of SST and high expression of their corresponding SSTRs on various endocrine tumors led to the clinical application of synthetic stable analogs of SST for hormonal treatment of human malignancies such as acromegaly." (PMID 33297556, 2020). "These SST analogs are widely used for the treatment of acromegaly, pancreatic neuroendocrine tumors, endocrine tumors of the gastroenterohepatic system, including carcinoid tumors, glucagonomas, gastrinomas, insulinomas, and VIPomas." (PMID 33297556, 2020). "Long-acting somatostatin analogues act as somatostatin receptor ligands and are widely used for the treatment of acromegaly either as adjuvant or as primary therapy." (PMID 22574156, 2012). "In our case, it is unclear whether some of his comorbidities were a result of acromegaly, such as his dilated cardiomyopathy and deafness, and whether these will improve with a somatostatin analog." (PMID 40584159, 2025). "Interestingly, despite the known side effects of somatostatin analogs, an increased percentage of acromegaly and NET patients are still given the maximum allowed analog dose, at least in some regions." (PMID 39329930, 2024). "The signalling pathways linked to acromegaly are also involved in mutation in guanine nucleotide-binding protein G(s) (GNAS1), the mutation that confers preferential responsiveness to GH inhibitory peptide SST." (PMID 38203605, 2023). "Therefore, the SST-SSTR axis is highly implicated in several human diseases, including acromegaly, cancers, and neurological disorders." (PMID 35446253, 2022). "SST analogues are approved for the treatment of acromegaly and carcinoid syndrome." (PMID 32272767, 2020). "In acromegaly, the improvement of lipid profile with SST analogues might be the result of a reduction in GH secretion." (PMID 30053852, 2018). "The clinical significance of the effect of somatostatin analogues on tumor shrinkage in patients with acromegaly has been further enhanced by the widespread use of long-acting somatostatin analogues as an alternative first-line therapy to surgical tumor resection." (PMID 22574156, 2012). "However, other mechanisms that could modify the biology of the GH-secreting pituitary tumor cannot be excluded; recent studies have found that somatostatin analogs pretreatment modulate aryl hydrocarbon receptor interacting protein in somatotroph adenomas." (PMID 23634209, 2013). "They suppress GH secretion because somatotroph adenomas, especially in DGSA, express somatostatin and dopamine receptors." (PMID 35498411, 2022).
acromegaly (continued). "Additionally, tamoxifen offers an additional, oral treatment option for patients with acromegaly who might not achieve biochemical targets or cannot tolerate conventional medical therapy (such as somatostatin analogs or growth hormone receptor antagonists), though additional studies are necessary." (PMID 33910628, 2021).
Hyperglycemia (25 papers, 2008 to 2024). An increased concentration of glucose in the blood. "Hyperglycemia suppresses ghrelin and is associated with a somatostatin release into the hypophyseal portal blood suppressing GH levels." (PMID 36874742, 2023). "This delay may be caused by the fish being stimulated to secrete glucagon and somatostatin hormones under the stress of hyperglycemia, thereby inhibiting the secretion of insulin and delaying the change in insulin in response to plasma glucose." (PMID 33178047, 2020). "As the authors discussed, it could be connected with the stimulation of somatostatin release from the hypothalamus by hyperglycemia, thus causing inhibition of growth hormone, as well as TSH secretion." (PMID 30945110, 2019). "Visfatin is upregulated by hypoxia, inflammation and hyperglycemia and downregulated by insulin, somatostatin and statins." (PMID 39424616, 2024). "Recent developments suggest that increased glucagon and decreased somatostatin secretion from the pancreas contribute to hyperglycaemia in type-2 diabetes (T2D) patients." (PMID 36834860, 2023). "Recently, the contribution of increased levels of circulating glucagon and decreased levels of somatostatin in type 1 and type 2 diabetes has been recognized as a contributor to hyperglycemia." (PMID 36834860, 2023). "During the subsequent studies in rat models in vivo, it was determined that both acute hypo-and hyperglycemia stimulate somatostatin mRNA, whereas GHRH mRNA is stimulated only by hyperglycemia." (PMID 33586392, 2021). "We note that the effects of HFD on somatostatin secretion—when mice remain largely normoglycaemic—are different from those observed once hyperglycaemia has developed." (PMID 32446876, 2020). "It will be argued that α-cell-intrinsic processes are most important for regulation of glucagon release during recovery from hypoglycaemia and that paracrine inhibition by somatostatin from the δ-cells shapes pulsatile glucagon release in hyperglycaemia." (PMID 27044660, 2016). "Further evidence for a role of somatostatin in the regulation of glucagon secretion in hyperglycaemia is obtained from the kinetics of secretion." (PMID 27044660, 2016). "Pulsatile hormone release from human and mouse islets is generated by hyperglycaemia with coinciding pulses of insulin and somatostatin that are synchronized in opposite phase to the glucagon pulses." (PMID 27044660, 2016). "Pasireotide showed a similar safety profile to that of other somatostatin analogues, except for the increased frequency and degree of hyperglycemia." (PMID 25537481, 2015). "Together, these findings suggest insulin or peripheral hyperglycemia may have effects on SST neurons and pituitary somatotrophs to control GH release in addition to the effects of low glucose on GHRH neurons." (PMID 33148883, 2020). "The bihormonal hypothesis was supported by studies that showed that suppression of glucagon with somatostatin limited the hyperglycaemia seen in patients with type 1 diabetes and alloxan-diabetic dogs." (PMID 29412829, 2018). "Given how SST plays a major role in the homeostasis of glucose metabolism, inhibiting the release of insulin, glucagon, and incretins, along with the fact that hyperglycemia is a known side effect of the administration of somatostatin analogues, this was somewhat surprising." (PMID 27399347, 2016). "Here we sought to determined a possible functional parallel between the enlargement of islet size in response to taurine supplementation, the number of islets, the resistance to glucose-induced hyperglycemia and the levels of the three main pancreatic peptides: insulin, glucagon and somatostatin." (PMID 20804628, 2010). "However, the elevation could be a result of a disturbed feedback mechanism due to neuropathy in the stomach, vagal neuropathy, an increased quantity of gastrin cells in the stomach, reduced number of somatostatin cells, or hyperglycaemia." (PMID 19243587, 2009).
Hyperglycemia (continued). "Hyperglycemia appears to directly affect the pituitary somatotrophs, reducing the GH release in response to GHRH or increasing the release of somatostatin." (PMID 33586392, 2021). "Within intact islets, hyperglycemia instead inhibits α-cell exocytosis, but not in T2D or when paracrine inhibition by insulin or somatostatin is blocked." (PMID 32312960, 2020). "Glucagon release is inhibited by hyperglycaemia, insulin, GLP-1 and somatostatin." (PMID 29412829, 2018). "Instead, hyperglycaemia inhibits α cell exocytosis, but not in the T2DM donor’s α cell or when paracrine inhibition by insulin or somatostatin is blocked." (PMID 34502413, 2021).